AR (androgen receptor)
Diseases named in the same sentence as AR in open-access papers (continued):
Sharing a sentence is not in itself a finding about the gene and the disease.
tumor (continued). "MAOA promoted PCa metastasis by regulating downstream ROS and Twist1 pathways that mediated Shh/Gli signaling to activate YAP1 transcription in concert with AR to induce epithelial–mesenchymal transition and tumor–stromal cell interactions." (PMID 36452480, 2022). "Luminal androgen receptor (LAR) tumours are characterised by high expression of androgen receptor (AR) and downstream AR targets, and enrichment of pathways involved in steroid synthesis, porphyrin metabolism, and androgen/oestrogen metabolism." (PMID 36003779, 2022). "Serving as E3 ubiquitin ligases of Brg1 and AR, the tumor suppressors FBW7 and SPOP, respectively, are frequently mutated in PCa7,28,36,37." (PMID 35233061, 2022). "A variety of strategies focusing on blocking androgen-AR signaling are available to treat PCa, and most have been shown to induce significant tumor regression and normalize serum PSA levels." (PMID 35185589, 2022). "CAV1 was already suggested to function as an androgen receptor co-regulator at advanced tumor stages." (PMID 35155239, 2022). "Nevertheless, any growing tumour requires neo-angiogenesis, which provides a potential for a combinatorial therapy targeting pro-angiogenic factors in concert with inhibition of AR signalling." (PMID 35513564, 2022). "Some hormones can activate relevant pathways by binding to related receptors, including ER and AR, and then promote tumor occurrence, development, and metastasis." (PMID 35370971, 2022). "This investigation aimed to clarify the association of the relative expression of five miRs (27a, 124, 130a, 488, and 506) and AR as possible tumor biomarkers in patients with CaP and nodular prostatic hyperplasia (NPH) from the northern region of Brazil." (PMID 35456428, 2022). "Unlike BET inhibitors, PROTAC 20 was able to suppress both AR signalling and AR levels and led to tumour regression in a CRPC mouse xenograft model." (PMID 35702740, 2022). "The inhibitor, called AZD5312 or ARRx, is a generation 2.5 of ASO that binds AR mRNA and inhibits the production of AR; the effect on tumor cells is represented by the inhibition of cellular growth and by the promotion of apoptosis." (PMID 36012138, 2022). "FOXA1 functions as a cofactor for AR and can promote tumor growth independently even in some AR deletion cases." (PMID 35860692, 2022). "Tissue-based methodologies permit to study AR and its localization at cellular level, both in tumor cells and in the surrounding stroma." (PMID 36111296, 2022). "As the AR has been reported to repress both PCa tumor suppressor genes and oncogenes, a deeper understanding of AR-mediated suppression will be vital to the development of future therapeutics which prevent the emergence of CRPC." (PMID 35018219, 2022). "In phase 1b, the recommended dose of 160 mg was administered to patients with androgen receptor expression in the tumor." (PMID 35330078, 2022). "Studies in cell line and xenograft models have indicated that increased ErbB2 signaling can contribute to the restoration of AR activity and tumor growth in CRPC." (PMID 35645241, 2022). "Let‐7 and miR‐299‐3p, on the other hand, function as tumor suppressor miRNAs that directly target AR and are frequently downregulated in aggressive PCa." (PMID 35612714, 2022). "Even in primary tissues not involved in sexual reproduction, such as bladder, sex steroids were shown to play a role in cancer: AR knockout and androgen depletion in mice suppressed tumor growth in the bladder in vitro and in vivo." (PMID 36288137, 2022). "Analysis of tumor immune infiltration showed that the expressions of AR and ERBB2 were correlated with the abundance of immune infiltration and made a difference in clinical outcomes." (PMID 35069767, 2022). "Oral administration of PROTAC 6 effectively reduced AR protein in the VCaP xenograft tumour tissue in mice and inhibits VCaP tumour growth." (PMID 35702041, 2022).
tumor (continued). "The figures they present show different expressions of AR protein in different regions of the tumor." (PMID 36361793, 2022). "Specifically, an interaction between the AR and β-catenin has been identified in PCa cells, directly augmenting tumor cell growth." (PMID 35902588, 2022). "This was confirmed in LNCaP xenografts, where PI3K inhibition plus AR inhibition led to a reduction of 24% in tumor size, compared to a single inhibition pathway or vehicle of 30–31% or 28% increase in tumor size, respectively." (PMID 36551776, 2022). "Kaplan-Meier curves revealed that patients bearing a primary tumor characterized by divergent AR and MYC transcriptional programs experienced distinct rates of clinical progression." (PMID 35562350, 2022). "On the contrary, the tumor suppressor NKX3.1 inhibits the juxtaposition mediated by AR of TMPRSS2 and ERG loci and promotes homology-directed repair, thereby disfavoring TMPRSS2-ERG fusion formation." (PMID 35267426, 2022). "High androgen levels in patients activate the AR pathway in tumor cells and manifest as endocrine resistance." (PMID 36556209, 2022). "After adjustment for age, nodal status, tumor stage, grade, and continuous AR expression, the trend became significant for IDFS (HR 0.91 (95% C.I. 0.96–1.00); p = 0.049), but not for BCSS and DRFI." (PMID 36577919, 2022). "miR-21 by itself is a direct transcriptional target of the androgen receptor (AR), but at the same time, it increases AR expression in PCa cell lines, potentially by targeting tumor suppressors." (PMID 35804929, 2022). "Thirty-six tumour-related genes including ALK, AR, BRCA2, FANCD2 and CBL were found to be mutated in all the three disease groups." (PMID 36686473, 2022). "In almost all PCa patients, the androgen receptor (AR) was the main driver of tumor cell genesis and development." (PMID 36452480, 2022). "In TCGA mRNA data for overall primary tumor samples (n = 1083), mir-29c positively correlated with AR and negatively correlated with CD276/B7H3." (PMID 36550153, 2022). "In this study, we also provided evidence that AR decoction inhibited tumor proliferation in CRC mice, and inhibited Wnt5/β-catenin signaling and the expression of ARF6 and N-Cadnerin in tumors of CRC mice." (PMID 34991661, 2022). "CRPC tumour cells have different genetic and epigenetic backgrounds, cell lineages, or evolutional stages (from being androgen-dependent to AR indifferent) within a tumour." (PMID 35832549, 2022). "A study including multiple isogenic tumor xenograft models demonstrated increased AR expression in recurrent tumor samples compared to paired androgen-sensitive samples." (PMID 35800367, 2022). "Although the expression of CHGA, NCAM1, and SYP varied among these three individuals, all of them showed a co-expression of AR and NE markers in the same areas of tumor sites." (PMID 36033483, 2022). "The cytotoxicity data reveal differential sensitivities of normal- and tumor-derived prostate epithelial cells following exposure to an AR antagonist and to two PARP inhibitors." (PMID 36970725, 2022). "Both Wnt and HER2 signalling pathways have the potential for positive feed-forward activation of AR activity, suggesting an androgen-independent activation of AR in these tumours." (PMID 36376977, 2022). "Further studies are needed to determine the extent to which AR antagonists can drive the cross-talk of intricate intercellular signaling networks between the tumor and stromal cells." (PMID 35864113, 2022). "For example, a study in 40 ESCC tumor tissues demonstrated high levels of AR expression in invasive ESCC tissues." (PMID 36142861, 2022). "ADT targets the androgen receptor (AR) to inhibit tumor progression as a first line of therapy in patients with hormone sensitive or castration sensitive prostate cancer (HSPC or CSPC)." (PMID 35669415, 2022). "Numerous studies have shown that androgen receptor (AR) signaling remains active to support tumor growth even at the CRPC stage." (PMID 35590370, 2022).
tumor (continued). "Theoretically, taxane-based chemotherapy should be effective against CRPC with constitutively active AR because its anti-tumor effect is exerted through a different mechanism, as a tubulin-stabilizing agent." (PMID 36289357, 2022). "This molecular activation has been related to tumor progression irrespective to AR signaling as well as a potential resistance mechanism to therapy." (PMID 36551557, 2022). "LAR cells partly depend on AR (androgen receptor) signaling, as demonstrated by the inhibition of cell viability and tumor growth when AR is targeted by bicalutamide, an AR antagonist, and are less likely to benefit from chemotherapy regimens." (PMID 36579519, 2022). "Next, we treated tumor slices prepared from two different AR-positive LuCaP models to mTOR inhibitors and mitochondrial metabolism." (PMID 35406510, 2022). "Our results showed that overexpression of ATF4 inhibited tumor growth and AR expression in a CAL-148 cell xenograft mouse model." (PMID 35013318, 2022). "This outlines a biologically coherent mechanism by which sdRNAs downregulate tumor suppressors in AR-PCa to enhance proliferative and metastatic capabilities and to encourage chemotherapeutic resistance." (PMID 35455981, 2022). "Then, IHC staining of SENP1 and UCHL1 was performed to evaluate their physiological relevance to AR and tumour progression." (PMID 35452181, 2022). "Darolutamide significantly inhibited cell growth and AR transcription activity in vitro while decreased tumor volume and serum prostate-specific antigen levels in vivo." (PMID 35645241, 2022). "In contrast, the derivative [111In]In-DOTA-Tz-TCO-Pip-AR bearing the piperidinyl linker showed lower uptake values in the tumor and pancreas, 3.2 ± 0.1 and 2.8 ± 0.5%I.D./g, respectively, at one-hour post-injection." (PMID 36559063, 2022). "Patients with AR expression tended to have lower tumor grade (p<0.001) but more lymph node involvement (p<0.01)." (PMID 35711833, 2022). "In the localized disease cohort, the results suggest that AR-mediated maintenance of a specific set of genes in mature prostate epithelium discourages de-differentiation and subsequent tumor aggressiveness." (PMID 35509021, 2022). "The expression of AR mRNA and proteins appears tightly regulated in benign prostate transit amplifying and basal epithelial cells (TA cells)." (PMID 35203681, 2022). "Using in vivo tissue recombination assays, we first examined if stromal AR action in Gli1-lineage cells acts as a tumor niche to support prostate epithelial oncogenesis." (PMID 36323713, 2022). "Numerous kinases and phosphatases interact with the AR and a shift in the phosphoproteome during tumor progression is observed in clinical samples." (PMID 35682963, 2022). "Overall, we show by CRISPR alteration that Foxp1 is a tumor suppressor by interfering with the AR pathway and Foxa1 is required for luminal cells’ identity." (PMID 36139541, 2022). "A large number of patients initially respond to androgen/AR-directed therapies, however over time patients inevitably relapse as tumor cells transform and become resistant to treatment, termed castrate-resistant prostate cancer (CRPC)." (PMID 36671452, 2022). "In the necrotic area, on average, the AR-positive cells accounted for 2–3%; in the enhancing tumor region, 90–95% in men and 85–95% in women; in the peritumoral area, 75–85% in men and 90–95% in women." (PMID 36361793, 2022). "The primary tumor and metastasis tissue showed variable immune-staining of Ki67, PSA, and AR in tumor epithelial cells both within and among cases." (PMID 36358614, 2022). "In this study, we observed an increase in AR expression in the enhancing tumor region (relative to the tumor core), allowing us to assume that the increased expression is required for further tumor progression." (PMID 36361793, 2022).
tumor (continued). "First, ELF3 was described as a tumour repressor of PCa by interfering with androgen receptor (AR) DNA binding, resulting in repression of AR target genes, which are drivers of PCa." (PMID 35472129, 2022). "Androgen deprivation therapy (ADT) and the second-generation androgen receptor (AR) targeting therapy were developed to suppress the androgen-activated intracellular cascade that leads to tumor progression and aggressive tumor growth." (PMID 34477955, 2022). "For mCRPC patients, drug resistance to 2nd-generation AR signaling inhibitors (ARSi), such as abiraterone and enzalutamide is essentially universal in tumor cells that often come with significantly elevated expression of truncated AR splice variant-7 (AR-V7)." (PMID 36009418, 2022). "Here we have investigated the role of AR and ER signaling using in vitro and immunocompromised models that eliminate any potential effects of the tumour microenvironment or immune infiltrates." (PMID 35618789, 2022). "Novel antiandrogens (enzalutamide or abiraterone) further prevent tumor progression by inhibiting the reactivated androgen and androgen receptor signaling in CRPC." (PMID 35177423, 2022). "Prohibitin, in addition to acting as a repressor, is also a target protein for AR, and its negative regulation promotes cell growth, which demonstrate its tumor suppressor function." (PMID 35456428, 2022). "KDM5D acts as a tumour suppressor in the prostate, where it interacts with the androgen receptor to down-regulate expression of AR target genes." (PMID 35406676, 2022). "The proto-oncogenic transcription factor c-Myc has been found to promote tumor growth in various AR-related cancers through AR signaling." (PMID 35886904, 2022). "These three m6A modification patterns closely correlate with androgen receptor signaling, stemness, proliferation and tumor immunogenicity of cancer cells, and stroma activity and immune landscape of tumor microenvironment (TME)." (PMID 35350771, 2022). "Our results showed that the overexpression of AR in CaP occurs in accordance with the deregulation of the expression of several microRNAs, which regulate the production of AR and present different quantifications of benign hyperplasia of the prostate." (PMID 35456428, 2022). "While synthetic androgens have proven to have undesired side effects, selective AR modulators (SARMs) have promising preclinical effects on reducing tumour burden in ER+ BC and have fewer side effects." (PMID 36376977, 2022). "We subsequently determined potential therapeutic effects of DCEM1 on 22RV1 (AR+) and PC-3 (AR–) xenograft tumor growth in SCID mice." (PMID 35653190, 2022). "In women, AR protein expression was statistically significantly higher between the tumor core and the peritumoral area (p = 0.0179611)." (PMID 36361793, 2022). "Kaplan–Meier analysis of patient survival was performed using cutoff values of 1.06 for AR/ER and 23% for residual tumor Ki67." (PMID 36556209, 2022). "In a PDX-CRPC mouse model, metformin reduced tumor volume and reduced PLCe gene expression and reduced Notch/Hes and AR signaling." (PMID 35327549, 2022). "The complex interactions involve numerous signaling pathways such as AR, tyrosine kinase receptor, angiogenesis, and tumor-immune escape." (PMID 35681683, 2022). "In most tumours that are resistant to AR antagonists, the AR signalling continues to be functional and drives tumour growth and progression." (PMID 35589670, 2022). "According to other studies, SIAH1 is a tumor suppressor involved in PC pathogenesis by repressing CPSF1-mediated AR-v7 generation and is a key regulatory factor." (PMID 36744180, 2022).
tumor (continued). "The CRPC LNCaP tumours are still responsive to ARPIs such as enzalutamide, emphasizing that these tumours still rely on ligand-dependent AR signalling." (PMID 35832549, 2022). "Mirna-224-5p-enriched exosomes secreted by non-small cell lung cancer (NSCLC) cells accelerated neoplasia by directly binding with the androgen receptor (AR)." (PMID 35255950, 2022). "In PC, BRCA1 co-regulates the AR activity mediating tumor progression, while BRCA2 limits the metastatic potential of PC by MMP9 downregulation and inhibition of the PI3K/AKT and MAP/ERK pathways (which also regulate PD-L1 expression)." (PMID 35203446, 2022). "Disseminated, hormone-sensitive PCa (HSPC) is managed with androgen deprivation therapy to target the androgen receptor (AR), but after a median of 24–36 months, the tumor recurs with re-activation of the AR as castration-resistant PCa (CRPC)." (PMID 34773073, 2022). "In our study, relevant data extracted from GEPIA showed that AR expression was positively associated with PFS in conventional RCC, which indicated its tumour suppressor role in RCC." (PMID 35452181, 2022). "To explore if this anti-tumor effect was AR-dependent, we analyzed AR activation status of C4-2B FR cells treated with OCM ABI or OCM CTRL." (PMID 36140255, 2022). "Apocrine BC’s strong association with AR highlights their importance as a model to understand AR signalling in BC, and these tumours should be enriched for clinical trials investigating AR-targeted agents." (PMID 36376977, 2022). "The evaluation of the therapeutic effected of tumor cells in vitro showed that increased AR expression promoted the migration and epithelial–mesenchymal transition process of EC cells and CSPCs." (PMID 35886904, 2022). "Shared dependence upon AR for tumor growth and survival provides an exciting opportunity to study AR signaling in a different cancer type and within a younger DSRCT-stricken patient population." (PMID 35650195, 2022). "Recently, an AR+ apocrine cell line model was shown to have an AR-dependent proliferative response to androgens and expression of genes that are normally expressed in ER+ luminal tumours." (PMID 36376977, 2022). "To further evaluate the AR regulatory function in DSRCT tumor mouse models, we performed ChIP-seq on DSRCT-xenograft and PDX samples." (PMID 35650195, 2022). "Significant to this issue, Julieta E. Laiseca’s group has reported that MAGE-A11 and MAGE-A6 form a protein complex leading to the MAGE-A11 stabilization and consequently the AR activity augmentation and promote tumor progression in prostate cancer." (PMID 35022469, 2022). "In the present study, we prospectively assessed AR-FL, AR-V7, and GR mRNA expression using tumor tissue from patients with CRPC to investigate the clinical relevance for prediction of treatment response." (PMID 36212458, 2022). "SHR3680, a novel AR antagonist, preclinically displayed comparable anti-tumor potency but with much less distribution in the brain and significantly decreased risk to induce seizure compared with enzalutamide." (PMID 35241087, 2022). "Conversely, 30% of the advanced and metastatic PCa cases progress due to AR bypass mechanisms, which allow tumor cells to survive in an AR-independent manner." (PMID 35686097, 2022). "One such AR-independent resistance mechanism is lineage plasticity, wherein tumor cells switch from an AR-driven, luminal differentiation program to an alternate differentiation program." (PMID 35909568, 2022). "In a study, when the hedgehog signaling pathway was inappropriately activated in OVCA, the two pathways end effector GLI3 and AR interacted physically and dependent functionally on each other to promote the growth and migration of malignant tumor cells." (PMID 35886904, 2022). "Haematoxylin‐eosin (HE) staining and IHC were implemented to detect the expression levels of NSUN2, AR and AR‐V7 using tumour tissues harvested from xenograft model mice." (PMID 36169095, 2022).